REM1 (RRAD and GEM like GTPase 1)
Description:
Promotes endothelial cell sprouting and actin cytoskeletal reorganization. May be involved in angiogenesis. May function in Ca(2+) signaling.
Synonyms: GES; GD:REM; formerly REM
Tractability: Small molecule: a structure with a bound ligand is known. Antibody: its Gene Ontology location is reachable by antibodies, with medium confidence.
Gene: Protein-coding gene on chromosome 20 (31,474,979 to 31,484,917, forward strand). Ensembl gene ENSG00000088320.
Gene Ontology:
Molecular function: calcium channel regulator activity; GTP binding; GTPase activity; transmembrane transporter binding
Cellular component: plasma membrane; I band; T-tubule
Genetic constraint (gnomAD): Loss-of-function variants: 16 observed, 23.07 expected, observed/expected ratio (o/e) 0.69, 90% interval 0.47 to 1.05. The upper end of that interval is the gene's LOEUF score, 1.05, which puts it in group 4 of 6, group 1 being the genes least tolerant of losing a copy. Missense variants: 381 observed, 351.56 expected, observed/expected ratio (o/e) 1.08, 90% interval 1 to 1.18. Synonymous variants: 142 observed, 145.5 expected, observed/expected ratio (o/e) 0.98, 90% interval 0.85 to 1.12.
Homologues: Orthologues: chimpanzee REM1 (99% identical), macaque REM1 (98% identical), rabbit REM1 (93% identical), dog REM1 (92% identical), guinea pig REM1 (91% identical), rat Rem1 (90% identical), mouse Rem1 (89% identical), pig REM1 (89% identical), tropical clawed frog rem1 (52% identical). Paralogues in human: RRAD (50% identical), GEM (49% identical), REM2 (42% identical), RASL12 (24% identical), RAP2A (21% identical), RIT2 (21% identical), RAP2B (21% identical), RERG (21% identical), RRAS (21% identical), RRAS2 (21% identical), RAP1B (20% identical), DIRAS2 (20% identical), and 23 more.
Diseases named in the same sentence as REM1 in open-access papers:
REM1 is named in the same sentence as 6 diseases in open-access papers, as found by Europe PMC text mining. Sharing a sentence is not in itself a finding about the gene and the disease. The quoted sentences say what the papers report.
viral infection (2 papers, 2018 to 2025). "We showed here that CPK3 diffusion in the PM is reduced upon activation as well as upon viral infection and that such immobilization depended on its substrate, Remorin (REM1.2), a scaffold protein." (PMID 40315285, 2025). "We then analyzed the capacity of REM1.3 phosphomutants to regulate PD aperture in the absence of viral infection." (PMID 30419072, 2018).
REM1 also shares sentences with these, for which no sentence is quoted: infection (2 papers); cyst (1); fibrosis (1); osteosarcoma (1); sarcoidosis (1).